ENSG00000300759 (novel transcript)
Gene: Long non-coding RNA gene on chromosome 18 (35,904,360 to 35,950,200, reverse strand). Ensembl gene ENSG00000300759.
Gene Ontology:
Biological process: miRNA-mediated post-transcriptional gene silencing
Cellular component: RISC complex